MTFR2 (mitochondrial fission regulator 2)
Description:
May play a role in mitochondrial aerobic respiration essentially in the testis. Can also promote mitochondrial fission (By similarity).
Synonyms: DUFD1; FAM54A
Tractability: PROTAC: ubiquitination databases record sites on it.
Gene: Protein-coding gene on chromosome 6 (136,231,024 to 136,250,571, reverse strand). Ensembl gene ENSG00000146410.
Subcellular location: Mitochondrion
Subcellular location (Human Protein Atlas): Vesicles
Gene Ontology:
Molecular function: protein binding
Biological process: aerobic respiration; mitochondrial fission; mitochondrion organization
Cellular component: mitochondrion
Genetic constraint (gnomAD): Loss-of-function variants: 29 observed, 27.18 expected, observed/expected ratio (o/e) 1.07, 90% interval 0.79 to 1.45. The upper end of that interval is the gene's LOEUF score, 1.45, which puts it in group 6 of 6, group 1 being the genes least tolerant of losing a copy. Missense variants: 367 observed, 389.17 expected, observed/expected ratio (o/e) 0.94, 90% interval 0.87 to 1.03. Synonymous variants: 123 observed, 133.24 expected, observed/expected ratio (o/e) 0.92, 90% interval 0.8 to 1.07.
Homologues: Orthologues: chimpanzee MTFR2 (98% identical), macaque MTFR2 (95% identical), rabbit MTFR2 (71% identical), dog MTFR2 (68% identical), pig MTFR2 (67% identical), guinea pig MTFR2 (66% identical), mouse Mtfr2 (60% identical), tropical clawed frog mtfr2 (36% identical), zebrafish mtfr2 (31% identical). Paralogues in human: MTFR1 (29% identical), MTFR1L (23% identical).
Diseases named in the same sentence as MTFR2 in open-access papers:
MTFR2 is named in the same sentence as 27 diseases in open-access papers, as found by Europe PMC text mining. Sharing a sentence is not in itself a finding about the gene and the disease. The quoted sentences say what the papers report.
breast carcinoma (12 papers, 2019 to 2025). "Previous studies disclose high expression of MTFR2 is correlated with tumor proliferation in breast cancer and gastric cancer." (PMID 38238834, 2024). "Whereas MTFR2 plays an important function in mitochondria and glycolysis, MTFR2 can be oxidatively phosphorylated into glycolysis for energy conversion in breast cancer cell glucose metabolism." (PMID 39871949, 2024). "MTFR2 was up-regulated in breast cancer and was related to age, lymph node metastasis, and prognosis in HER2 positive breast cancer patients." (PMID 34039308, 2021). "In detail, in the Oncomine database, MTFR2 was highly expressed in breast cancer, colorectal cancer, gastric cancer, lung cancer and other tumor tissues, while lowly- expressed in brain nerve tumor, breast cancer, leukemia and other tumor tissues." (PMID 34039308, 2021). "At present, studies found that the expression of MTFR2 in breast cancer tissues were increased, and was correlated to the clinicopathological features and poor prognosis of patients." (PMID 34039308, 2021). "Knockout of MTFR2 prohibited the proliferation, migration and invasion of breast cancer cells, and blocked epithelial-stromal transformation (EMT)." (PMID 34039308, 2021). "Interfering with MTFR2 inhibited the growth and migration of breast cancer cells, indicating its biological role as oncogene and with prognostic value." (PMID 34039308, 2021). "Colony formation assays and CCK-8 assays revealed that higher levels of MTFR2 showed higher proliferation rates in breast cancer cell lines." (PMID 31740625, 2019). "Recently, the expression and physiological functions of MTFR2 in breast cancer were investigated." (PMID 36192752, 2022). "Furthermore, they revealed that MTFR2 improved proliferation, invasion and aerobic glycolysis in breast cancer cells via regulating Hif1α and Hif2α." (PMID 36192752, 2022). "Next, we investigated whether expression levels of PIMREG, CEP55, and MTFR2 is related to the expressions of BCSC markers in breast cancer cell lines." (PMID 33718103, 2020). "Taken together, these findings suggest that MTFR2 could serve as a new therapeutic target in breast cancer." (PMID 31740625, 2019). "Furthermore, our data showed that the overexpression of MTFR2 could promote breast cancer cell progression." (PMID 31740625, 2019). "The deletion also encompassed MTFR2 and BCLAF1 genes, the latter one was recently related to the regulation of the PDL1 pathway in breast cancer." (PMID 39239354, 2024). "In breast cancer, MTFR2 expression was related to HER2 status and indicated a poor breast cancer prognosis." (PMID 35600359, 2022). "Published studies have also proven that MTFR2 plays an essential role in switching OXPHOS to glycolysis, activating the signaling pathway that promotes cell proliferation, invasion, and migration in oral squamous carcinoma and breast carcinoma." (PMID 35600359, 2022). "In addition, MTFR2, which belongs to the same family as MTFR1, promotes the progression of breast cancer and oral squamous carcinoma when its expression is dysregulated." (PMID 34926459, 2021).
glioma (6 papers, 2018 to 2022). A benign or malignant brain and spinal cord tumor that arises from glial cells (astrocytes, oligodendrocytes, ependymal cells). "In glioblastoma, MTFR2 can transcriptionally regulate TTK expression in maintaining glioma stem-like cells." (PMID 35600359, 2022). "In glioma stem-like cells (GSCs), the MTFR2-dependent regulation of TTK was validated for a crucial role in maintaining GSCs in gliomas." (PMID 32121037, 2020). "Another study showed that MTFR2 could regulate tumor genesis, drug resistance, and tumor recurrence in glioma by activating TTK signaling." (PMID 35600359, 2022). "MTFR2-dependent TTK regulation played a key role in maintaining GSC (Glioma stem-like cells) in glioma, and may be a target molecule of new drugs for glioma patients." (PMID 34039308, 2021). "MTFR2 was also identified as an activator of TTK promoter in glioma stem-like cells." (PMID 33718103, 2020). "A recent study revealed that MTFR2 was significantly elevated in glioma samples and that higher MTFR2 expression could be correlated with poor prognosis." (PMID 31740625, 2019). "Expression data from Rembrandt database indicated that MTFR2 was significantly elevated in GBM samples when compared to other subtypes of glioma or normal brain tissue and higher MTFR2 expression could be correlated with poor prognosis." (PMID 29423030, 2018).
lung adenocarcinoma (5 papers, 2021 to 2025). A carcinoma that arises from the lung and is characterized by the presence of malignant glandular epithelial cells. "Compared with normal tissues, the expression of MTFR2 is upregulated, such as cervical cancer, renal clear cell carcinoma, lung adenocarcinoma, colon cancer, and other tumors." (PMID 40129972, 2024). "Although our study is the first to identify the role of MTFR2 in lung adenocarcinoma, there are still some limitations." (PMID 35600359, 2022). "Taken together, MTFR2 could serve as a novel prognostic indicator and therapeutic target for lung adenocarcinoma." (PMID 35600359, 2022). "Recent studies indicate that it also participates in cancer carcinogenesis and development; however, the clinical significance of MTFR2 in lung adenocarcinoma has not been fully confirmed." (PMID 35600359, 2022). "However, the relationship between MTFR2 with lung adenocarcinoma (LUAD) had not been reported." (PMID 34039308, 2021).
gastric cancer (4 papers, 2021 to 2024). A primary or metastatic malignant neoplasm involving the stomach. "Some studies have reported that downregulation of MTFR2 inhibits the proliferation, invasion and migration of gastric cancer cells in vitro and in vivo." (PMID 39871949, 2024).
oral squamous cell carcinoma (3 papers, 2024 to 2025). "In this study, we demonstrated that Brucea javanica oil could inhibit the proliferation, invasion and metastasis of oral squamous cell carcinoma by down-regulating MTFR2-mediated aerobic glycolysis and modulating the SOD2/H2O2 signaling pathway." (PMID 39871949, 2024).
colorectal cancer (2 papers, 2021 to 2024). A primary or metastatic malignant neoplasm that affects the colon or rectum. "Additionally, another study demonstrated that HOXC10 overexpression activated MTFR2 expression, thereby enhancing the proliferation, clone formation, invasion, and migration of colorectal cancer cells." (PMID 40129972, 2024).
endometrial cancer (2 papers, 2024 to 2026). Primary or metastatic malignant neoplasm involving the endometrium (mucous membrane that lines the endometrial cavity). "In this study, we observed elevated levels of MTFR2 in endometrial cancer, which were associated with unfavorable clinical outcomes." (PMID 40129972, 2024). "Further investigation into the functions of MTFR2 in endometrial cancer is warranted, considering its potential involvement in the pathogenesis and progression of various tumor types." (PMID 40129972, 2024). "To further confirm the role of MTFR2 in promoting endometrial cancer oncogenesis, we established a xenograft model by subcutaneously injecting MTFR2-silenced HEC-1A cells into mice." (PMID 40129972, 2024). "Collectively, these findings provide compelling evidence supporting the negative regulatory role of miR-132-3p in the oncogenic activity of MTFR2 in endometrial cancer." (PMID 40129972, 2024). "Our findings highlight the critical role of MTFR2 in promoting endometrial cancer cell proliferation and growth through the miR-132-3p/PI3K/Akt signaling pathway." (PMID 40129972, 2024). "The findings revealed elevated MTFR2 expression in endometrial cancer, which subsequently facilitated tumor cell proliferation via the activation of the phosphatidylinositol-4, 5-bisphosphate 3-kinase (PI3K)-protein kinase B (Akt) signaling pathway." (PMID 40129972, 2024). "The findings of this study emphasize the importance of MTFR2 in the development of endometrial cancer and suggest its potential as a therapeutic target." (PMID 40129972, 2024). "Our present study further supports the notion that MTFR2 plays critical roles in promoting endometrial cancer cell growth by facilitating cell cycle progression and suppressing apoptosis." (PMID 40129972, 2024). "Gain-of-function and loss-of-function approaches were utilized to investigate the impact of MTFR2 on endometrial cancer cell proliferation and tumorigenesis in both in vitro and in vivo settings." (PMID 40129972, 2024). "In summary, our study highlights the significant upregulation of MTFR2 in endometrial cancer, which leads to the activation of the PI3K/Akt signaling pathway and plays a crucial role in promoting tumor cell proliferation." (PMID 40129972, 2024). "The results of the KEGG analysis revealed a significant enrichment of the PI3K/Akt signaling pathway in MTFR2-upregulated cases, suggesting its potential role as a key contributor to endometrial cancer progression." (PMID 40129972, 2024). "The expression of MTFR2 in endometrial cancer was analyzed using The Cancer Genome Atlas (TCGA) dataset and detected in endometrial cancer tissues and cells, respectively." (PMID 40129972, 2024). "Functional studies show that MTFR2 promoted the proliferation, migration and invasion of endometrial cancer cells." (PMID 40129972, 2024). "To gain further insights into the molecular mechanism by which MTFR2 influences endometrial cancer progression, we conducted bioinformatic analysis." (PMID 40129972, 2024). "In our study, we corroborated the up-regulation of MTFR2 expression in endometrial carcinoma through analysis of the TCGA database." (PMID 40129972, 2024). "Immunohistochemical analysis revealed elevated MTFR2 expression in various types of endometrial carcinoma tissues." (PMID 40129972, 2024). "The expression of MTFR2 is enhanced in endometrial carcinoma, and it is positively correlated with the poor prognosis of patients." (PMID 40129972, 2024). "Additionally, three genes—MRPL15, MTFR2, and MTHFD2—were found functionally linked to MRS2, and their upregulation is associated with unfavorable outcomes in endometrial cancer patients." (PMID 41551444, 2026). "In this study, we investigated the role of MTFR2 in endometrial cancer cell." (PMID 40129972, 2024).
endometrial cancer (continued). "Notably, higher MTFR2 expression was significantly correlated with reduced overall survival probability and relapse-free survival, indicating the potential of MTFR2 as a prognostic marker for endometrial cancer studies." (PMID 40129972, 2024). "Notably, overexpression of miR-132-3p led to significant downregulation of MTFR2 in endometrial cancer tissues." (PMID 40129972, 2024). "The objective of this study was to investigate the role of MTFR2 in endometrial cancer." (PMID 40129972, 2024). "Finally, our data establish MTFR2 and miRNA-132-3p as a novel and promising prognostic biomarker for patients with endometrial cancer." (PMID 40129972, 2024). "Moreover, we elucidated the role of MTFR2 in promoting endometrial cancer tumorigenesis through the activation of the PI3K/Akt signaling pathway." (PMID 40129972, 2024). "Furthermore, PCR and WB experiments confirmed the significant up-regulation of MTFR2 expression in five endometrial carcinoma cell lines." (PMID 40129972, 2024). "In TCGA, MTFR2 was significantly overexpressed in endometrial carcinoma tissues, whether compared with paired or unpaired normal endometrial tissues." (PMID 40129972, 2024). "Additionally, our analysis of clinical correlations and survival predictions indicated that MTFR2 could serve as a reliable prognostic marker for endometrial cancer diagnosis." (PMID 40129972, 2024).
hepatocellular carcinoma (2 papers, 2024 to 2025). A malignant tumor that arises from hepatocytes. "For instance, a previous study reported that a prognostic signature comprising 10 mitochondrial dynamics genes, including MTFR2, played crucial roles in mitochondrial fission and had the potential to serve as important predictors and therapeutic targets for hepatocellular carcinoma." (PMID 40129972, 2024). "In the tumor margin of hepatocellular carcinoma (HCC), activated hepatic stellate cells upregulate MTFR2, initiating inhibiting DRP1 degradation and mitochondrial fission." (PMID 40365837, 2025).
lung carcinoma (2 papers, 2021 to 2022). "Cell colony formation assay, CCK-8 assay, cell cycle assay, and transwell assay were performed to verify the cell proliferation, migration, and invasion abilities after interfering with MTFR2 in lung cancer cells." (PMID 35600359, 2022). "We also treated cells with SC79, an AKT agonist, to examine whether the activation of AKT signaling could reverse the inhibitory effect of MTFR2 knockdown on lung cancer cells." (PMID 35600359, 2022). "Moreover, for lung cancer, limited bioinformatics studies have demonstrated that MTFR2 was a biomarker for diagnosis and poor prognosis in LUAD." (PMID 35600359, 2022). "The GSE31210 dataset also showed a higher MTFR2 expression in lung cancer tissues." (PMID 35600359, 2022). "Western blot showed that knockdown of MTFR2 inhibited the activation of the AKT pathway and SC79 can partially reduce si-MTFR2-induced decreased p-AKT and Cyclin D1 expression, suggesting that MTFR2 could regulate lung cancer proliferation through the AKT signaling pathway." (PMID 35600359, 2022).
clear cell carcinoma (1 paper, 2024). "Finally, IHC staining further confirmed that MTFR2 was highly expressed in endometrial adenocarcinoma, serous carcinoma and clear cell carcinoma." (PMID 40129972, 2024).
lymph node metastasis (1 paper, 2019). "Multivariate analysis demonstrated that MTFR2 expression (HR, 1.96; 95% CI, 1.55-2.48; p=0.03) and lymph node metastasis (HR, 1.91; 95% CI, 1.43-2.56; p=0.02) were independent prognostic factors for OS." (PMID 31740625, 2019).
oral cancer (1 paper, 2025). "In oral cancer research, HOX genes such as HOXC10 are continuously upregulated from precancerous lesions to malignant stages, and the HOXC10-encoded protein can bind to the MTFR2 promoter region to promote transcription." (PMID 40748969, 2025).
pancreatic cancer (1 paper, 2021). "In all three databases, MTFR2 mRNA expression in gastric, breast, colon, cervical, ovarian, and pancreatic cancer, was significantly higher than that in normal tissue." (PMID 33995638, 2021).